OAS3 (2'-5'-oligoadenylate synthetase 3)
Description:
Interferon-induced, dsRNA-activated antiviral enzyme which plays a critical role in cellular innate antiviral response. In addition, it may also play a role in other cellular processes such as apoptosis, cell growth, differentiation and gene regulation. Catalyzes preferentially the dimerization of ATP to form 2'-5'-diadenylate (2-5A), but can also form the trimeric 2'-5'-oligoadenylate. The oligoadenylate then binds to the inactive monomeric form of ribonuclease L (RNase L) leading to its dimerization and subsequent activation. Activation of RNase L leads to degradation of cellular as well as viral RNA, resulting in the inhibition of protein synthesis, thus terminating viral replication. Can mediate the antiviral effect via the classical RNase L-dependent pathway or an alternative antiviral pathway independent of RNase L. Displays antiviral activity against Chikungunya virus (CHIKV), Dengue virus, Sindbis virus (SINV) and Semliki forest virus (SFV).
Synonyms: p100OAS; p100
Tractability: Antibody: its Gene Ontology location is reachable by antibodies, with high confidence. PROTAC: ubiquitination databases record sites on it; its protein half-life has been measured.
Gene: Protein-coding gene on chromosome 12 (112,938,051 to 112,976,460, forward strand). Ensembl gene ENSG00000111331.
Subcellular location: Cytoplasm; Nucleus
Subcellular location (Human Protein Atlas): Cytosol; Nucleoplasm; Plasma membrane
Pathways (Reactome):
Immune System: Interferon alpha/beta signaling; Interferon gamma signaling; OAS antiviral response
Gene Ontology:
Molecular function: 2'-5'-oligoadenylate synthetase activity; ATP binding; double-stranded RNA binding; protein binding; nucleotidyltransferase activity
Biological process: cellular response to exogenous dsRNA; defense response to bacterium; defense response to virus; MDA-5 signaling pathway; negative regulation of chemokine (C-C motif) ligand 5 production; negative regulation of chemokine (C-X-C motif) ligand 2 production; negative regulation of chemokine (C-X-C motif) ligand 9 production; negative regulation of IP-10 production; negative regulation of type I interferon-mediated signaling pathway; negative regulation of viral genome replication; positive regulation of interferon-beta production; positive regulation of monocyte chemotactic protein-1 production; positive regulation of tumor necrosis factor production; regulation of ribonuclease activity; response to virus; RIG-I signaling pathway; antiviral innate immune response; interleukin-27-mediated signaling pathway; nucleobase-containing compound metabolic process; type I interferon-mediated signaling pathway; defense response
Cellular component: cytoplasm; cytosol; extracellular region; nucleoplasm; intracellular membrane-bounded organelle; membrane; nucleus
Genetic constraint (gnomAD): Loss-of-function variants: 108 observed, 113.91 expected, observed/expected ratio (o/e) 0.95, 90% interval 0.81 to 1.11. The upper end of that interval is the gene's LOEUF score, 1.11, which puts it in group 4 of 6, group 1 being the genes least tolerant of losing a copy. Missense variants: 1,258 observed, 1,399.8 expected, observed/expected ratio (o/e) 0.9, 90% interval 0.86 to 0.94. Synonymous variants: 552 observed, 587.69 expected, observed/expected ratio (o/e) 0.94, 90% interval 0.88 to 1.01.
Homologues: Orthologues: chimpanzee OAS3 (99% identical), macaque OAS3 (93% identical), dog OAS3 (78% identical), guinea pig OAS3 (72% identical), mouse Oas3 (70% identical), rat Oas3 (70% identical), rabbit OAS3 (69% identical). Paralogues in human: OAS2 (30% identical), OAS1 (19% identical), OASL (13% identical).
Diseases named in the same sentence as OAS3 in open-access papers:
OAS3 is named in the same sentence as 84 diseases in open-access papers, as found by Europe PMC text mining. Sharing a sentence is not in itself a finding about the gene and the disease. The quoted sentences say what the papers report.
COVID-19 (57 papers, 2020 to 2026). A disease caused by infection with severe acute respiratory syndrome coronavirus 2. "OAS1 (2'-5'-oligoadenylate synthetase 1) and OAS3 have been identified through a genome-wide association study as major loci associated with COVID-19." (PMID 41977153, 2026). "The distribution of genotypes for the ACE2 rs2074192, IFNAR2 rs2236757, OAS1 rs10774671, and OAS3 rs10735079 polymorphisms conformed to HWE in both the COVID-19 and control groups (p > 0.05)." (PMID 39296547, 2024). "The C allele and the C/G genotype of the rs1293767 OAS2 genetic variant and the T allele and the C/T genotype of the rs2285932 genetic variant of OAS3 had lower odds of developing COVID-19 symptoms among the studied Mexican population." (PMID 38673053, 2024). "Logistic regression analysis under five genetic models adjusted for age, sex, smoking history, DM, hypertension, and CAD was used to investigate the association of IFNAR2 rs2236757 and OAS3 rs10735079 polymorphisms with COVID-19 signs and symptoms." (PMID 37745867, 2023). "The variant rs10735079 lies in the interferon-inducible OAS gene cluster (OAS1, OAS2, and OAS3) and was associated with critical COVID-19 illness (P = 1.65 × 10−8) in genome-wide significant associations." (PMID 37745867, 2023). "The COVID-19-risk variants in the OAS1/OAS3/OAS2 locus were also associated with reduced expression of OAS3 in certain T cell subsets but not in monocytes, NK cells, or B cells." (PMID 34799557, 2021). "In addition, the functional variants OAS1 rs4767027C>T, OAS1 rs1131454A>G, and OAS3 rs10735079A>G have also been associated with susceptibility to and/or severity of COVID-19." (PMID 41977153, 2026). "This suggests that variations in these genes, such as OAS1 and OAS3, might influence our susceptibility to severe COVID-19." (PMID 39296547, 2024). "Additionally, individuals with the T allele of the gene variant rs2285932 (OAS3) had a 61% lower chance of exhibiting COVID-19 symptoms (OR = 0.39; 95% CI: 0.2–0.9)." (PMID 38673053, 2024). "Interestingly, we also observe a colocalization in this locus between OAS3 eQTL and COVID-19 GWAS locus; however, in this case, the alternative allele of rs10774671 is linked to an increase in the OAS3 gene expression level." (PMID 37308670, 2023). "Interestingly, OAS3 was identified as a genetic susceptibility marker in severe COVID-19 disease and is found to be differentially expressed in severe COVID-19 patients in our analysis." (PMID 34899680, 2021). "The effect of OAS3 SNPs that associate with COVID-19 is still unclear." (PMID 34342578, 2021). "Therefore, the aim of this study was to determine whether four variants in the OAS1 and OAS3 genes are associated with susceptibility to COVID-19 and with the clinical signs and symptoms of the disease." (PMID 41977153, 2026). "However, the direction of the eQTL effect was opposite for the two genes: OAS1 gene expression is downregulated by the alternative allele of the COVID-19 GWAS index SNP rs10774671G>A, whereas the expression level of OAS3 gene is upregulated by the alternative allele." (PMID 37308670, 2023). "OAS1, OAS2, and OAS3 were overexpressed in hospitalized patients with severe COVID-19 compared with healthy subjects (HS) (log2 fold change [95% CI]: OAS2: 4.312 [4.161-4.602], OAS3: 1.660 [1.485-1.916]; p = 0.0040 for both)." (PMID 41899113, 2026). "In this study, we examined the frequency of three gene variants within the OAS family (OAS1, OAS2, and OAS3) and one in RNASEL, in relation to the manifestation of COVID-19 symptoms and the overall disease prognosis." (PMID 38673053, 2024). "In this study, we analyzed the frequency of three gene variants of OAS (OAS1, OAS2, and OAS3) and one in RNASEL, and evaluated their association with the occurrence of COVID-19 symptoms and disease outcome." (PMID 38673053, 2024).
COVID-19 (continued). "Another study highlighted that a Neanderthal-derived haplotype encompassing the genes OAS1, OAS2, and OAS3 conferred protection against COVID-19, with OAS3 showing the most substantial correlations." (PMID 38673053, 2024). "Regression analysis showed that COVID-19 susceptibility in children increases in cases of interactions of IFNAR2 rs2236757, OAS1 rs10774671, OAS3 rs10735079, CD40 rs4813003 and CASP3 rs113420705." (PMID 37896870, 2023). "Single nucleotide variant rs10735079 (A > G) is responsible for gene clusters OAS1, OAS2 and OAS3, and is among the COVID-19 genes." (PMID 37896870, 2023). "We perform fine-mapping of the OAS1 locus, associated with COVID-19, to reveal the imbalanced expression of OAS1 and OAS3 genes during the antiviral innate immune response." (PMID 37308670, 2023). "We identified accessible proxy SNPs in LD with the COVID-19 sentinel rs10774671 in the promoter of OAS3, and accessible proxies interacting with OAS1 and OAS2 in all immune cell types analyzed." (PMID 35659055, 2022). "IFNAR2 was significantly upregulated in severe COVID-19 patients (FDR = 0.0075), and both OAS1 and OAS3 were upregulated in T cells from severe COVID-19 patients compared to those with mild disease." (PMID 35659055, 2022). "In summary, our search for target genes in the severe COVID-19-risk loci in chromosome 12 revealed three putative causal eGenes that display prominent cell-type-restricted effects—OAS1 in NCM, OAS3 in T-cell subsets, and DTX1 in B cells." (PMID 34799557, 2021). "This study investigated the potential influence of SNPs in genes associated with the interferon pathway (IFNAR2 rs2236757), antiviral response (OAS1 rs10774671, OAS3 rs10735079), and viral entry (ACE2 rs2074192) on COVID-19 severity and their association with MAFLD." (PMID 39296547, 2024). "In our study, individuals carrying the heterozygous C/T genotype of the OAS3 gene variant rs2285932 were at a 50% reduced risk of developing COVID-19 symptoms compared to those without this genotype (OR = 0.50; 95% CI: 0.19–1.31)." (PMID 38673053, 2024). "Similarly, decreased expression of multiple IFN-I-inducible genes including MX1, OAS3 and OASL has been associated with persistent symptoms after COVID-19." (PMID 38532465, 2024). "However, in the case of gene interactions, the significant impact of OAS3 rs10735079 was shown on SARS-CoV-2 susceptibility, but it was not shown to be involved in the prediction of MIS-C or severe COVID-19 development." (PMID 37896870, 2023). "Therefore, based on the model, the key components of COVID-19 susceptibility in childhood are alleles of genes IFNAR2 rs2236757, OAS1 rs10774671, OAS3 rs10735079, CD40 rs4813003 and CASP3 rs113420705." (PMID 37896870, 2023). "The COVID-19 dataset revealed CAMP (AUC: 0.692), LTF (AUC: 0.764), DEFA1B (AUC: 0.701), SAMD9(AUC: 0.786), GBP1(AUC: 0.757), DDX60 (AUC: 0.802), DEFA4 (AUC: 0.763), and OAS3(AUC: 0.801) that exhibited superior diagnostic capabilities." (PMID 38115996, 2023). "In addition to the OAS1 eQTL, OAS3 eQTL in fibroblasts was also colocalized with the COVID-19 GWAS locus (posterior probability = 0.99)." (PMID 37308670, 2023). "There were no statistical differences between OAS3 rs10735079 genotypes and allele frequencies between children with different degrees of COVID-19 severity and healthy children." (PMID 37896870, 2023). "We functionally annotated several additional variants within OAS1 and OAS3 that were significantly associated with COVID-19 hospitalization in patients of European ancestry but did not yet reach significance in patients of African ancestry." (PMID 35835913, 2022). "Some studies suggest that OAS gene family may provide a potential therapeutic target for COVID-19 if the gene is mutated on chromosome 12q24.13 (a gene cluster that encodes OAS1, OAS2, and OAS3 antiviral restriction enzyme activators)." (PMID 36162993, 2022).
COVID-19 (continued). "In addition, we found that colocalized severe COVID-19-risk variants in another independent locus (chromosome 12) were also associated with reduced expression of two interferon-inducible genes (OAS1 and OAS3)." (PMID 34799557, 2021). "association P value = 1.05 × 10−6) specifically in patrolling non-classical monocytes (NCM), whereas OAS3 showed prominent eQTLs in T-cell subsets, highlighting cell type-restricted effects of COVID-19-risk variants." (PMID 34799557, 2021). "Genes associated with the IFN pathway, such as IFI27, IFIT1, IFIT2, OASL and OAS3, showed significantly higher expression levels, in particular individuals with long COVID-19 when compared to non-long COVID-19 and the organoid systems infected with the alpha variant." (PMID 40055791, 2025). "Overall, these results suggest that the pleiotropic association of the OAS1/2/3 locus with multiple diseases, including severe COVID-19, might be explained, at least partially, by transcriptional deregulation of all three OAS genes by regulatory variants lying within the OAS3 Epromoter." (PMID 39727170, 2025). "Genetic variations within IFNAR2, OAS1, and OAS3 could potentially disrupt this signaling pathway, leading to decreased protein abundance, impaired receptor internalization, or altered ligand interactions, thereby exacerbating the severity of COVID-19." (PMID 40278335, 2025). "Consistently, genes (e.g., ISG15, IFITM1/2/3, OAS3 and IFIT1/2/3) associated with the IFN-response pathway, especially for IFN-I response, were significantly upregulated in COVID-19 associated acute necrotizing encephalopathy compared with healthy donors and other COVID-19 groups." (PMID 37848421, 2023). "Furthermore, this CA dimension correlated with a subset of blood neutrophils that specifically expressed ISGs such as IFIT1, RSAD2, and OAS3 but also PD-L1, suggesting that a high-viral load in the lung can significantly influence the blood immune landscape in COVID-19 patients." (PMID 33674591, 2021). "This study highlights the significant impact of genetic variations in IFNAR2, OAS1, OAS3, and ACE2 on the clinical and laboratory outcomes of COVID-19 patients receiving Paxlovid treatment." (PMID 40278335, 2025). "Through COVID-19-relevant transcriptome and enrichment gene sets, seven druggable targets with COVID-19-relevant functions were identified, including CCR9, CXCR6, XCR1, IL10RB, OAS1, OAS2, and OAS3." (PMID 37886583, 2023). "Results demonstrated that OAS1, OAS2, OAS3, and OASL were all highly expressed in SARS-CoV-2 infected NHBE (OAS 1 − 3, P < 0.01) and in the blood leucocytes of COVID-19 patients (all P < 0.001)." (PMID 36949448, 2023). "Twelve proteins showed lower levels in critical patients (fold-changes 1.20–3.58), of which OAS3 and COG5 found their expression increased after COVID-19 specific therapy." (PMID 35022497, 2022). "Seven of our significant genes higher (GALNT14, OAS1, CCRL2, OAS3, CCR1, OAS2, SIPA1L2) in COVID-19 and two lower (HLA-DPB1, HLA-DQA2) were identified to overlap." (PMID 34335605, 2021). "OAS1, OAS2, OAS3, IFIT1, IFIT3, IFI44, IFI44L and IFITM1: Current COVID-19 genetic studies incline to analyze those genes together." (PMID 34109284, 2021). "Several other loci show no previously documented genome-wide significant associations, despite the high significance and attractive candidate genes for COVID-19 (for example, CXCR6, LZTFL1, IFNAR2 and OAS1/OAS2/OAS3 loci)." (PMID 34237774, 2021). "Our research indicated that certain polymorphisms in the genes ACE2 rs2074192, IFNAR2 rs2236757, OAS1 rs10774671, OAS3 rs10735079, CD40 rs4813003, FCGR2A rs1801274 and CASP3 rs113420705 could predict cytokine responses in pediatric COVID-19 patients." (PMID 40066463, 2025). "Interestingly, given the important role of type I interferon (IFN-I) in COVID-19, we also found decreased expression of multiple IFN-I-inducible genes including MX1, OAS3, and OASL." (PMID 35027067, 2022).
COVID-19 (continued). "Finally, in individuals with moderate SARS-CoV-2 infection, 2’-5’-Oligoadenylate Synthetase 1 (OAS1), OAS2, OAS3, and T cell Immunoreceptor with Ig and ITIM domains (TIGIT) were elevated, but these levels significantly decreased with increased COVID-19 severity." (PMID 39928675, 2025). "Furthermore, we did not observe statistically significant differences in COVID-19 severity between patients with either OAS1 rs10774671 or OAS3 rs10735079." (PMID 39296547, 2024). "The frequency of ACE2 rs2074192, IFNAR2 rs2236757, OAS3 rs10735079, FCGR2A rs1801274 and CASP3 rs113420705 genotypes did not follow the Hardy–Weinberg equilibrium (p < 0.05) due to the directional selection made in our study (focusing on patients with COVID-19)." (PMID 37896870, 2023). "To illustrate, the expression levels of OAS3, a member of the OAS antiviral effector protein family, show similar levels between symptomatic and symptom-free participants in the SARS-CoV-2 negative group, but show different levels in the COVID-19 positive group." (PMID 38532465, 2024).